CAD (carbamoyl-phosphate synthetase 2, aspartate transcarbamylase, and dihydroorotase)
Diseases named in the same sentence as CAD in open-access papers (continued):
Sharing a sentence is not in itself a finding about the gene and the disease.
infection (24 papers, 2012 to 2025). The state of being infected such as from the introduction of a foreign agent such as serum, vaccine, antigenic substance or organism. "While none of the early genes implicated in lignin biosynthesis were upregulated after infection with U. maydis wild type, we observed transcriptional effects for four of the six CAD genes acting at a late step of the lignin pathway." (PMID 24473076, 2014). "We noted a significant up-regulation in the expression of CCR (cinnamoyl-Co A reductase) and CAD (cinnamoyl alcohol dehydrogenase) during pathogen infection, with a more rapid response in the cultivar XN511." (PMID 40699547, 2025). "Of the five CAD genes found within the phenylpropanoid metabolic pathway, Zm00014d005093 showed noticeably greater expression in the middle stages of infection in both OE and SL lines than in the early and late stages." (PMID 41304614, 2025). "In EV-A71 infected Vero cells, an upregulation of CAD expression was observed during infection and viral replication is reduced when depleting CAD." (PMID 40608831, 2025). "A moderate, albeit consistent, reduction in CAD S1859 phosphorylation was observed in the context of vΔVGF infection relative to WT-VACV infection, in serum-starved asparagine-containing medium." (PMID 39817770, 2025). "CAD genes gradually decreased after infection in G28, except for CAD1-2, which showed the highest expression level at 5 d." (PMID 37701805, 2023). "In CBH, four CAD genes were induced suddenly after infection and presented maximum expression levels at 1 d, followed by a decline." (PMID 37701805, 2023). "Inhibition of the cell infection by CaD was observed at all MOI showing a trend to more efficient inhibition at higher MOI values." (PMID 36207386, 2022). "Taken together, these data inferns that CaD can be potentially used to prevent cell infection with SARS-CoV-2 and urge further research towards clinical testing of this substance for the therapy of covid-19 patients." (PMID 36207386, 2022). "To study the exact metabolic pathways involved, we examined the temporal changes in the expression of glutamine metabolism-related enzymes, including glutaminase (GLS), GDH and CAD, in host cells during infection." (PMID 32085644, 2020). "Glutamine metabolism-related enzymes, such as GDH and the carbamoyl-phosphate synthetase 2, aspartate transcarbamylase, and dihydroorotase (CAD), increase in expression with time after infection." (PMID 32085644, 2020). "Further supporting the importance of CAD for the EBOV lifecycle is the fact that the de novo pyrimidine synthesis activity of CAD is a prerequisite for cell division, which has been suggested to be necessary for productive infection of cells with EBOV." (PMID 32370067, 2020). "Notably, the supplementation of the VGF peptide upon vΔVGF infection compensates for the reduced phosphorylation levels of CAD and S6K1." (PMID 39817770, 2025). "During infection with other viruses, such as Hepatitis D virus (HDV), vaccinia (VACV), Kaposi’s sarcoma-associated herpesvirus (KSHV) or SARS-CoV-2, CAD has been described to be activated during infection and this activation was described to be important for viral replication and NF-κB inactivation." (PMID 40608831, 2025). "Furthermore, WT KSHV infection potently enhanced CAD S1900 phosphorylation, whose effect was minimal during ∆Cyclin infection." (PMID 38365882, 2024). "We found that the host proteins HDAC1 and CAD play a key role in the FMDV infection process." (PMID 37162335, 2023). "Similarly, the expression of CAD increased substantially at 4 h p.i., and remained elevated throughout the course of infection." (PMID 32085644, 2020). "Therefore, the ICP0-induced loss of CAD-associated CENP-I, -O, -P, and -Q and NAC-associated CENP-C, -H, -N, and -M observed during infection or transfection of GFP-CENP-expressing cells is most likely reflecting the complete breakdown of the whole proteinaceous structure." (PMID 23028505, 2012).
infection (continued). "Our results indicated that the activities of PAL, C4H, 4CL, CAD, and POD were stimulated upon fungal pathogen infection, leading to an increase in lignin accumulation." (PMID 40278064, 2025). "In comparison with the wild type, they were both significantly reduced in terms of virulence when infection assays were performed using the treated conidia of M. oryzae or C. acutatum by CAD1, CAD5, CAD7, or CAD-Con." (PMID 37239456, 2023). "Infection with P. cinnamomi of either control or elicited holm oak ELs was mainly characterized by overexpression of CS, PAL, and CAD genes, and by higher contents in JA and, in a less extent, in ellagic acid." (PMID 35356118, 2022). "Then, to gain insight into the role of HS in the CaD mediated inhibition, we treated HUVECs with Heparinase III for 1 h prior infection." (PMID 36207386, 2022). "In this study, we elucidate the mechanism by which CAD phosphorylation S1859 is activated through the phosphorylation of S6K1 at T389, a known substrate of the mTORC1 complex, especially upon nutrient restriction during infection." (PMID 39817770, 2025). "In the context of vΔVGF infection, as opposed to WT-VACV infection, a notable reduction in CAD phosphorylation at S1859 was observed." (PMID 39817770, 2025). "Although differences were not significant, we observed a trend of increased expression of CS, PAL, and CAD genes after infection with oomycete in lines E00 and Q8, but not in the VA5 line." (PMID 35356118, 2022). "Interestingly, the treatment of HFF cells with VGF peptide in the absence of infection does not markedly increase the phosphorylation levels of CAD at S1859 and S6K1 T389." (PMID 39817770, 2025). "On the contrary, CaD did not affect cell infection with VSVG-expressing lentivirus." (PMID 36207386, 2022). "Our data reveal that in the presence of glutamine, or asparagine, upon infection, HFF cells maintain similar levels of CAD phosphorylation at S1859 and T456, independent of VGF." (PMID 39817770, 2025). "Extending our investigation to determine the necessity of mTORC1-S6K1 activation for CAD phosphorylation at S1859, HFF cells were treated with the mTORC1 inhibitor rapamycin upon VACV-infection at a concentration that did not affect cell viability." (PMID 39817770, 2025). "These outcomes indicate that in the context of vΔVGF infection, the VGF peptide can compensate for the absence of VGF for activation of CAD and mTORC1 signaling." (PMID 39817770, 2025). "The VGF peptide, in isolation, is capable of activating the EGFR pathway; however, it cannot independently phosphorylate CAD and S6K1 in the absence of infection." (PMID 39817770, 2025). "Nonetheless, in the absence of such infection, the VGF peptide alone does not replicate these effects, indicating the requirement for additional viral factors/processes that synergize with VGF for the activation of CAD and S6K1 upon VACV infection." (PMID 39817770, 2025).
metabolic disease (2 papers, 2021 to 2025). A congenital disorder (due to inherited enzyme abnormality) or acquired (due to failure of a metabolically important organ) disorder resulting from an abnormal metabolic process. "Except for CAD, mutations of any enzymes involved in the de novo pyrimidine biosynthesis pathway also lead to metabolic diseases." (PMID 34638594, 2021).
neurodegenerative disease (2 papers, 2021 to 2024). A disorder of the central nervous system characterized by gradual and progressive loss of neural tissue and neurologic function. "Although CaD has been described to enhance NO synthase in the endothelium, CaD acts as an antioxidant and may play a role in the neuromodulation of brain functions in aging and neurodegenerative diseases through both stress mechanisms." (PMID 33922431, 2021).
genetic disorder (1 paper, 2022). "EIEE-50 is an autosomal invisible genetic disorder caused by a CAD mutation that encodes a multifunctional enzyme complex involved in de novo pyrimidine biosynthesis." (PMID 35356445, 2022).
CAD also shares sentences with these, for which no sentence is quoted: leukemia (4 papers); childhood cancer (3); COVID-19 (2); Encephalopathy (2); Fanconi anemia (2); acute coronary syndrome (1); and soft tissue tumors (1); anemia (1); Aortic dissection (1); autism (1); B-cell lymphoma (1); bladder urothelial carcinoma (1); cervical cancer (1); childhood tumors (1); Cirrhosis (1); citrullinemia type I (1); CNS tumors (1); cystic kidneys (1); diabetic neuropathy (1); early infantile epileptic encephalopathy (1); esophageal squamous cell carcinoma (1); gastric tumor (1); haematological tumours (1); hematologic malignancies (1); Hyperammonemia (1); Hyperglycemia (1); malignant peripheral nerve sheath tumor (1); maple syrup urine disease (1); mastitis (1); meningitis (1).
A further 22 diseases each share a sentence with CAD in 1 paper.